MYL12B (myosin light chain 12B)
Description:
Myosin regulatory subunit that plays an important role in regulation of both smooth muscle and nonmuscle cell contractile activity via its phosphorylation. Phosphorylation triggers actin polymerization in vascular smooth muscle. Implicated in cytokinesis, receptor capping, and cell locomotion.
Synonyms: MRLC2; MLC-B
Tractability: PROTAC: ubiquitination databases record sites on it; its protein half-life has been measured.
Gene: Protein-coding gene on chromosome 18 (3,261,479 to 3,278,461, forward strand). Ensembl gene ENSG00000118680.
Pathways (Reactome):
Signal Transduction: RHO GTPases Activate ROCKs; RHO GTPases activate CIT; RHO GTPases activate PAKs; RHO GTPases activate PKNs
Developmental Biology: EPHA-mediated growth cone collapse; Sema4D induced cell migration and growth-cone collapse
Muscle contraction: Smooth Muscle Contraction
Gene Ontology:
Molecular function: protein binding; myosin heavy chain binding; calcium ion binding
Cellular component: cell cortex; extracellular exosome; cytoplasm; cytosol; myofibril; myosin II complex; stress fiber; apical part of cell; brush border; Z disc
Genetic constraint (gnomAD): Loss-of-function variants: 3 observed, 12.62 expected, observed/expected ratio (o/e) 0.24, 90% interval 0.11 to 0.61. The upper end of that interval is the gene's LOEUF score, 0.61, which puts it in group 2 of 6, group 1 being the genes least tolerant of losing a copy. Missense variants: 120 observed, 217.75 expected, observed/expected ratio (o/e) 0.55, 90% interval 0.47 to 0.64. Synonymous variants: 57 observed, 72.83 expected, observed/expected ratio (o/e) 0.78, 90% interval 0.63 to 0.98.
Homologues: Orthologues: chimpanzee MYL12B (100% identical), mouse Myl12b (100% identical), pig MYL12B (100% identical), rat Myl12b (100% identical), dog MYL12B (99% identical), tropical clawed frog myl12b (95% identical), zebrafish myl12.2 (95% identical), Caenorhabditis elegans mlc-1 (49% identical), Caenorhabditis elegans mlc-2 (49% identical). Paralogues in human: MYL12A (98% identical), MYL9 (93% identical), MYL2 (55% identical), MYL11 (55% identical), MYL5 (55% identical), MYL10 (53% identical), MYL7 (49% identical).
Diseases named in the same sentence as MYL12B in open-access papers:
MYL12B is named in the same sentence as 21 diseases in open-access papers, as found by Europe PMC text mining. Sharing a sentence is not in itself a finding about the gene and the disease. The quoted sentences say what the papers report.
Sepsis (2 papers, 2015 to 2025). Sepsis is defined as life-threatening organ dysfunction caused by a dysregulated host response to infection. "Key genes we identified, such as RPL10, MYL12B, and PPIA, have been shown to play significant roles in the mechanisms associated with sepsis and AKI." (PMID 40428155, 2025).
bipolar disorder (1 paper, 2015). A disorder of the brain that causes unusual shifts in mood, energy, activity levels and the ability to carry out day-to-day tasks. "The result showed that 6 genes (including MAD1L1, JAM3, MYL12B, MYL12A, ITIH1 and RYR2) had been reported to be significant associated with bipolar disorder in at least one genetic study." (PMID 26193471, 2015).
colitis (1 paper, 2020). Inflammation of the colon. "To this end, we used a DSS-induced colitis model, which was established by treating wild-type C57BL/6 mice with 2% DSS, which was administered in their drinking water for 7 days, and used an antibody that can detect Myl9, Myl12a, and Myl12b." (PMID 33584659, 2020).
glioma (1 paper, 2020). A benign or malignant brain and spinal cord tumor that arises from glial cells (astrocytes, oligodendrocytes, ependymal cells). "Therefore, above studies of MYL and myosin II both on schizophrenia and glioma accorded with our findings that MYL12B was expressed lower in schizophrenia and was found decreasing DSS when glioma grade increasing." (PMID 32565801, 2020). "CAMK2D, EIF3K, MPC2, MYL12B, PAM, and SLC35B4, selected from the schizophrenia dataset and TCGA, were reevaluated in CGGA through gene expression in glioma grading and survival curves between patients having high level of gene expression and those having low level of gene expression." (PMID 32565801, 2020).
hepatocellular carcinoma (1 paper, 2024). A malignant tumor that arises from hepatocytes. "The interaction of MYL12B with MAFG-AS1 promotes the proliferation and migration of hepatocellular carcinoma cells, and CYP27B1 is a risk gene for malignant tumors and other chronic diseases." (PMID 39394698, 2024).
melanoma (1 paper, 2022). A malignant, usually aggressive tumor composed of atypical, neoplastic melanocytes. "We also observed upregulated genes in siLMNB1 melanoma cells, like MYL12B." (PMID 35883595, 2022).
cancer (3 papers, 2008 to 2025). A tumor composed of atypical neoplastic, often pleomorphic cells that invade other tissues. "Additionally, MYL12B, with an average correlation of 0.24, is known to be involved in the regulation of cell morphology with links to cancer progression." (PMID 39934114, 2025).
tumor (3 papers, 2017 to 2024). "Among the eight upregulated genes observed for cell adhesion, migration, and invasion, we detected three genes positively regulating cell adhesion and affecting tumor dissemination (Ptpn14, Myl12b, and Emp2)." (PMID 29108266, 2017). "Then, silencing lnc-MAFG-AS1 expression is found to impede the tumor progression of HCC both in vitro and in vivo by interacting with NM IIA subunits (MYH9, MYL12B, and MYL6)." (PMID 36034393, 2022).
MYL12B also shares sentences with these, for which no sentence is quoted: airway hyperresponsiveness (1 paper); asthma (1); breast carcinoma (1); colon cancer (1); COVID-19 (1); Dysmenorrhea (1); Hypertension (1); Insulin resistance (1); nasopharyngeal carcinoma (1); retinoblastoma (1); Salmonella Infections (1); schizophrenia (1); septic shock (1).